FGF23 (fibroblast growth factor 23)
Diseases named in the same sentence as FGF23 in open-access papers (continued):
Sharing a sentence is not in itself a finding about the gene and the disease.
hypophosphatemia (continued). "Patients with XLH have hypophosphatemia with low levels of renal phosphate reabsorption, normal serum calcium levels, elevated serum alkaline phosphatase activities, normal or increased parathyroid hormone levels, normal or increased 1,25-dihydroxyvitamin D3 levels, and elevated FGF23 levels." (PMID 32257293, 2020). "Elevated concentrations of FGF23 are responsible for impaired bone mineralization and so for more frequent fractures even if it is not simple to discriminate disease burden effects from phosphaturia/hypophosphatemia effects, because of correlation between FGF-23 levels and disease burden." (PMID 32849305, 2020). "Based on clinical evidence obtained from patients after kidney transplantation, the use of rapamycin, an mTORC1 inhibitor, has been shown to cause hypophosphatemia associated with the impaired renal reabsorption of Pi20,21; however, this has not been associated with alterations in FGF23 levels." (PMID 33299044, 2020). "Duration of therapy possibly should be 3-6 months or more since it is demonstrated that in kidney transplant patients high FGF23 levels may sustain for this period even when overt hypophosphatemia exists, suggesting autonomous FGF23 production, which vanishes only after time." (PMID 32130720, 2020). "FGF23-mediated upregulation of prostaglandin E2 (PGE2) via inhibition of proximal tubule phosphate transport may also contribute to hypophosphatemia, but the supporting evidence is less clear, since these animal studies were not supported by a subsequent under-powered crossover study in children." (PMID 30808384, 2019). "Therefore, chronic FGF23 excess leads to vitamin D-resistant hypophosphatemia." (PMID 30627598, 2019). "Meanwhile, elevated levels of serum FGF23 increase urinary phosphate excretion by downregulating renal sodium-phosphate transporters, and limit intestinal phosphate absorption by restricting active vitamin D synthesis to levels that are abnormally low or normal despite hypophosphatemia." (PMID 30808384, 2019). "However, hypophosphatemia with high FGF23 was later reported in some surviving patients." (PMID 29515522, 2018). "Therefore, we cannot exclude that further stimulation of circulating FGF23, e.g., by increased phosphate load may result in pathological cardiac remodeling in Hyp mice despite the presence of hypophosphatemia." (PMID 29977226, 2018). "The pathognomonic features of excess circulating FGF23 are renal tubular wasting of phosphate and suppressed 1,25-dihydroxy vitamin D levels which further impair intestinal absorption of phosphate worsening hypophosphatemia and resulting in impaired mineralization of bone." (PMID 27709474, 2016). "Interestingly, upregulation of Fgf23 expression and hypophosphatemia are observed in these mice." (PMID 25873956, 2015). "However, there is controversy about whether PTH or FGF-23 plays a dominant role in post-transplant hypophosphatemia." (PMID 24605319, 2014). "However, more recent data suggest that oral phosphate supplementation may be ineffective in correcting post-transplant hypophosphatemia, as it further stimulates FGF-23 secretion." (PMID 24605319, 2014). "However, despite a higher FGF23 concentration and associated greater urinary phosphate excretion, the BD children showed no signs of hypophosphatemia." (PMID 22465847, 2012). "Therefore, our data suggest that hypocalcemia and hypophosphatemia are a consequence rather than a cause of high-level Fgf23 in the SFFV-FGF2 animals." (PMID 22629419, 2012). "Furthermore, hypophosphatemia which is the major stimulant for FGF-23 secretion is resolved." (PMID 20107581, 2009). "FD lesions can overproduce fibroblast growth factor-23 (FGF-23), leading to renal phosphate wasting, hypophosphatemia, and impaired bone mineralization." (PMID 42100588, 2026).
hypophosphatemia (continued). "The identification of elevated FGF-23 levels in FAM20A-related ERS with severe nephrolithiasis and hypophosphatemia raises the question of the interest of burosumab as targeted therapy." (PMID 41645214, 2026). "Our model of XLHR is similar to the well‐studied Hyp mouse model: both have osteomalacic bone, hypophosphatemia, abnormal serum calcium and ALP levels, growth plate defects, and elevated FGF23 levels." (PMID 41172247, 2026). "The resulting excess circulating levels of fibroblast growth factor 23 (FGF23) lead to renal phosphate wasting and hypophosphatemia." (PMID 41185884, 2025). "FD lesions produce excess phosphaturic hormone fibroblast growth factor 23 (FGF23), leading to hyperphosphaturia in most patients, and hypophosphatemia in those with high FD burden." (PMID 41480037, 2025). "Although the increase of FGF23 is a common feature in patients with MAS, only the patients with extensive bone involvement are prone to develop hypophosphatemia." (PMID 40491596, 2025). "Acquired FGF23-mediated hypophosphatemic osteomalacia includes TIO, fibrous dysplasia, iron-infused hypophosphatemia, and post-renal transplant hypophosphatemia." (PMID 41445556, 2025). "High FGF23 levels are responsible for the main clinical manifestations of XLH, such as hypophosphatemia, rickets, and bone mineralization defects." (PMID 40926139, 2025). "PHEX malfunction results in increased levels of the phosphaturic hormone fibroblast-growth factor 23 (FGF23) with consecutive renal phosphate wasting, suppressed synthesis of 1,25-dihydroxyvitamin D and hypophosphatemia." (PMID 40493262, 2025). "Fibroblast growth factor-23 (FGF-23) is a phosphaturic hormone produced by osteocytes, and excessive activity leads to renal phosphate wasting and hypophosphatemia." (PMID 41583152, 2025). "Hypophosphatemia with urinary phosphate wasting, indicated by low TmP/GFR, should be differentiated as FGF23-mediated or FGF23-independent." (PMID 41445556, 2025). "The diagnosis of XLH is established in the presence of persistent hypophosphatemia, low tubular phosphate reabsorption relative to glomerular filtration rate (TmP/GFR), and, in most cases, elevated or inappropriately normal FGF23 levels." (PMID 41467153, 2025). "In this article, we reported a patient with chronic refractory hypophosphatemia due to TIO who is treated with burosumab, a monoclonal antibody that targets and blocks the activity of FGF23." (PMID 40922882, 2025). "These pathogenic variants result in elevated circulating levels of fibroblast growth factor 23 (FGF23), responsible for the main clinical manifestations of XLH, such as hypophosphatemia, skeletal deformities, and mineralization defects." (PMID 40926139, 2025). "Biochemical parameters demonstrated hypophosphatemia, hyperphosphaturia, slight increase in parathyroid hormone (PTH), high levels of alkaline phosphatase, and elevated FGF23." (PMID 39416269, 2024). "The patientpresented here had hypophosphatemia and hyperphosphaturia (TmP/GFR) but intact FGF23,calcitriol, calcium, and PTH concentrations were all within the reported reference ranges." (PMID 38746050, 2024). "Other diseases that cause acquired hypophosphatasemia due to increased levels of FGF23 are tumor-induced rickets/osteomalacia (TIO), hypophosphatemia following intravenous iron infusion, and biliary atresia." (PMID 38732094, 2024). "Fibroblast growth factor 23 (FGF23) has also been identified as a factor responsible for tumor-induced osteomalacia, a rare paraneoplastic syndrome characterized by hypophosphatemia." (PMID 36776964, 2023). "Elevated serum fibroblast growth factor 23 (FGF23) level and hypophosphatemia indicated the diagnosis of TIO." (PMID 37417620, 2023). "While this study supports potential beneficial effects of the use of FGF23 blockade in ARHR disorders, we also show that the full correction of hypophosphatemia is insufficient to fully correct bone growth and mineralization." (PMID 37943605, 2023).
hypophosphatemia (continued). "Animal studies indicate that loss of PHEX function results in enhanced secretion of the phosphaturic hormone fibroblast growth factor 23 (FGF23), which leads to renal phosphate wasting, hypophosphatemia and insufficient calcitriol (1,25(OH)2D) synthesis." (PMID 36544157, 2022). "However, it remains unclear to what extent correction of hypophosphatemia is able to rescue the mineralization defect because the effect of anti-FGF23 therapy on the local levels of mineralization inhibitors, such as ASARM peptides, osteopontin, and PPi, is not known." (PMID 36278488, 2022). "Hypophosphatemia, decreased Tmp/GFR, and high FGF23 levels are the characteristic biochemical features." (PMID 36499221, 2022). "Randomized control trials (RCTs) have shown that certain intravenous iron preparations can induce high levels of fibroblast growth factor 23 (FGF‐23) and persistent hypophosphatemia." (PMID 35426179, 2022). "Calcitriol synthesis, and consequently Ca/Pi serum levels, are increased by hypocalcemia, hypophosphatemia, and PTH while are decreased by calcitriol and FGF23." (PMID 34199067, 2021). "Biochemical hallmarks of XLHR include hypophosphatemia, increased ALP, and elevated serum levels of FGF23." (PMID 34199067, 2021). "Can inhibition of excessive FGF-23 activity help to improve biochemical, morphological and histological alterations in the muscle of patients with FGF-23-related hypophosphatemia?" (PMID 34650980, 2021). "Elevated levels of FGF23 have been quantified in a majority of XLH patients and hypophosphatemia mice, an orthologous animal model of XLH." (PMID 34572066, 2021). "The results in the current study indicated a new entity of acquired FGF23-related hypophosphatemia other than TIO and iron infusion-induced FGF23-related hypophosphatemia." (PMID 34901334, 2021). "In order to counteract hypophosphatemia in FGF-2HMWtg mice, a promising approach was achieved by a continuous high phosphate diet, which was able to normalize the exaggerated serum FGF-23 level." (PMID 33396566, 2020). "His mother and sister both had hypophosphatemia, elevated ALP enzyme activities, and high intact FGF23 levels." (PMID 32257293, 2020). "His initial biochemical profile revealed persistent hypophosphatemia, decreased %TRP, and inappropriately normal serum FGF‐23 level." (PMID 31372587, 2019). "Although hypophosphatemia is the primary link between elevated FGF23 and the pathophysiology of XLH, FGF23 has recently been proposed to also contribute to XLH via other molecular mechanisms." (PMID 30808384, 2019). "Post-cleavage C-terminal fragments of FGF23 have also been shown to block formation of FGF23-FGFR-KLOTHO complexes and to improve hypophosphatemia, which adds another regulatory level to FGF23 signalling." (PMID 30808384, 2019). "Biochemical analyses revealed persistent hypophosphatemia, decreased %TRP, elevated serum FGF‐23, and low 1,25(OH)2D, suggesting TIO (patient 2)." (PMID 31372587, 2019). "Having established that hypophosphatemia is due to FD-related FGF-23-induced renal phosphate wasting, treatment is similar to other disorders of FGF-23 excess." (PMID 31196103, 2019). "Additionally, other rare disorders may manifest as FGF23-mediated hypophosphatemia, including osteoglophonic dysplasia, McCune–Albright syndrome, epidermal nevus syndrome, neurofibromatosis, hypophosphatemic rickets with hyperparathyroidism and Jansen metaphyseal chondrodysplasia." (PMID 29652819, 2018). "Several lines of evidence indicate that phosphate-fibroblast growth factor-23 (FGF23) signaling pathways deserve attention in patients with COPD, in whom a tendency for hypophosphatemia has been described." (PMID 30236113, 2018). "Although FGF23 levels were similar in both groups, it is inappropriately normal for the ADPKD cohort, given the hypophosphatemia in the latter." (PMID 29326910, 2017).
hypophosphatemia (continued). "Acquired hypophosphatemia due to renal phosphate wasting is most likely due to TIO, in which case excess FGF23 is most often produced by benign, small phosphaturic mesenchymal tumors." (PMID 27709474, 2016). "Our experiments also show SPR4-peptide infusion induces changes in Wild type mice that mimic aspects of the HYP mice phenotype (suppressed FGF23, PTH with hypophosphatemia)." (PMID 24839967, 2014). "WT-SPR4 mice developed hypophosphatemia and hypercalcemia with increased PTH, FGF23 and 1.25(OH)2D3." (PMID 24839967, 2014). "Together with our results, it is conceivable that genetic activation of FGFR1 in bones leads to elevated FGF23 in OGD, resulting in hypophosphatemia." (PMID 23451204, 2013). "Circulatory FGF23 is elevated in most patients with XLH, and high level of intact FGF23 despite hypophosphatemia is a clinical indicator in XLH diagnosis." (PMID 23028440, 2012). "Taken together, high FGF23 levels in the setting of hypophosphatemia do neither induce tubular injury nor promote the accumulation of immune cells or the formation of TLS." (PMID 41384828, 2025). "Burosumab’s efficacy in XLH or FGF23-mediated hypophosphatemia with PHEX PV is well documented; however, its effectiveness in non-XLH FGF23-mediated hypophosphatemia is based on case reports and small studies of TIO." (PMID 41445556, 2025). "Loss-of-function mutations of the PHEX gene lead to the increase of circulating fibroblast growth factor 23 (FGF23), resulting in hypophosphatemia by reducing resorption of phosphate in the renal proximal tubule and synthesis of 1,25-dihydroxyvitamin D (1,25-(OH)2D3)." (PMID 40331725, 2025). "Burosumab should be considered as an effective and safe alternative strategy for FGF23-mediated hypophosphatemia in FD/MAS for those who either cannot tolerate or do not respond to conventional therapy." (PMID 40297189, 2025). "Burosumab should be considered as an effective and safe alternative strategy for FGF23-mediated hypophosphatemia in FD/MAS for those who either cannot tolerate or do not respond to the association of vitamin D analog and phosphate supplements." (PMID 40297189, 2025). "For example, when FGF23 is ectopically oversecreted from a PMT in a patient with TIO or another organ, including the liver, orthotopic FGF23 expression in the bone should be suppressed to compensate for hypophosphatemia." (PMID 39963340, 2025). "Tumor-induced osteomalacia (TIO) is a rare paraneoplastic syndrome characterized by fibroblast growth factor-23 (FGF-23) overproduction from mesenchymal tumors, leading to renal phosphate wasting, hypophosphatemia, and impaired 1,25-dihydroxyvitamin D (1,25 Vit D) synthesis." (PMID 40951211, 2025). "Non-suppressed FGF23 concentrations in the setting of hypophosphatemia support the diagnosis of FGF23-mediated renal hypophosphatemia." (PMID 40295317, 2025). "In the case of ectopic oversecretion of FGF23, including TIO, in which FGF23 is secreted from PMTs originating in soft or skeletal tissue, FGF23 expression in normal bone should be suppressed to compensate for hypophosphatemia." (PMID 39963340, 2025). "Patients with FGF23-mediated hypophosphatemia, regardless of their PHEX PV status, face the same management issues with conventional therapy." (PMID 41445556, 2025). "Although FGF23 does not regulate and therefore does not affect transplacental Ca and P transport, its non-physiological increase in the mother induces hypophosphatemia, hypocalcemia, hypovitaminosis D, and secondary hyperparathyroidism." (PMID 40636514, 2025). "Tumor-induced osteomalacia (TIO) is an uncommon paraneoplastic syndrome caused by small, benign mesenchymal tumors that secrete the phosphaturic hormone, fibroblast growth factor 23 (FGF23), leading to hypophosphatemia and skeletal pain, fractures and muscle fatigue." (PMID 39314547, 2024).
hypophosphatemia (continued). "Similar observations were noted in ovarian cancer patients, in whom both serum levels and immunohistochemistry staining of FGF23 correlated with an advanced stage of the disease but not with hypophosphatemia." (PMID 38397231, 2024). "Although hepatic production of FGF23 has been suggested in chronic settings, there are no data indicating hypophosphatemia resulting from acute hepatic FGF23 production." (PMID 39525686, 2024). "The purpose of this study was to investigate the potential of TM5614 as a therapeutic agent for the treatment of congenital FGF23‐related hypophosphatemic rickets and osteomalacia in humans by administering TM5614 to Hyp mice and examining its curative effect on hypophosphatemia." (PMID 38050660, 2024). "Our data indicate that oral administration of TM5614 ameliorates hypophosphatemia in Hyp mice, suggesting that TM5614 may be an effective treatment for congenital FGF23‐related hypophosphatemic rickets and osteomalacia." (PMID 38050660, 2024). "A differential effect in terms of hypophosphatemia has been noted following administration of FCM, which may be related to fibroblast growth factor 23 (FGF23)." (PMID 38347520, 2024). "A significant positive correlation was found between serum FGF23 concentrations and stage of disease, but no patient with an elevated FGF23 concentration had hypophosphatemia." (PMID 38806758, 2024). "In addition to the preoperative steps, the behavior of FGF23 and PTH induced an increase in phosphaturia and consequent hypophosphatemia." (PMID 39462348, 2024). "Biochemical evaluation at admission showed hypophosphatemia due to low renal tubular reabsorption of phosphate (TmP/GFR: 1.70 mg/dL) and increased serum intact FGF23 value (iFGF23) (190 pg/mL, n.v.: < 95 pg/mL, DiaSorin kit, Stillwater, MN, USA) suggestive of TIO." (PMID 37436671, 2023). "Therefore, correction of hypophosphatemia in the face of residual FGF23 elevations is insufficient to correct the bone phenotype associated with ARHR in the long term and the residual bone phenotype might be due to persistent FGF23 elevations and/or DMP1 deficiency." (PMID 37943605, 2023). "Laboratory evaluation shows hypophosphatemia, elevated alkaline phosphatase (ALP), and normal serum calcium levels, whereas parathormone (PTH) may be normal or increased and FGF23 greatly increased." (PMID 36011303, 2022). "If no other alterations are found, serum FGF23 measurement should be undertaken to direct the diagnosis of FGF23-independent hypophosphatemia." (PMID 36499221, 2022). "A 62-year-old-woman with a suspected Tumor-induced-osteomalacia (TIO), a rare neoplastic syndrome that results in renal phosphate wasting with hypophosphatemia, underwent 68Ga-DOTATOC PET/CT on the suspicion of a mesenchymal tumor producing Fibroblast growth factor 23 (FGF23)." (PMID 35204480, 2022). "Laboratory tests revealed hypophosphatemia with normal parathyroid hormone (PTH) levels, normal serum calcium, high 24-hour urine calcium, normal 1,25-dihydroxyvitaminD levels, low renal threshold phosphate concentration (TmPO4/GFR), and high FGF23." (PMID 35145798, 2022). "In addition to these limitations on dosing, SFO increases fibroblast growth factor-23 (FGF23), which can lead to hypophosphatemia, biochemical changes in bone turnover, and an increased risk of osteomalacia." (PMID 35790696, 2022). "It has been suggested that, in XLH, these lesions are not related to the hypophosphatemia but occur as a direct effect of increased FGF23 expression." (PMID 35101067, 2022). "Fibroblast growth factor 23 (FGF23), another hormonal mediator, also participates in phosphorus regulation in order to match bone mineralization, counteracts the effects of vitamin D, and plays a key role in malignancy-induced hypophosphatemia." (PMID 35145817, 2022). "Hypophosphatemia persisted unchanged in the follow-up, while FGF23 was confirmed increased; TIO-related symptoms did not resolve." (PMID 35381903, 2022).